TTR (transthyretin)
Diseases named in the same sentence as TTR in open-access papers (continued):
Sharing a sentence is not in itself a finding about the gene and the disease.
amyloidosis (continued). "Wild‐type transthyretin (ATTRwt) amyloidosis is the most common systemic amyloidosis in Western countries and manifests mainly as progressive restrictive cardiomyopathy." (PMID 33274477, 2021). "In fact, recently, patisiran represents the world’s first siRNA-based drug that is FDA-approved for the treatment of hereditary transthyretin-mediated amyloidosis via transthyretin (TTR) gene silencing." (PMID 34571731, 2021). "As the TTR protein is primarily produced in the liver, in mutant TTR amyloidosis liver transplantation or combined liver and heart transplantation has been performed in highly selected patients." (PMID 34524619, 2021). "The presence of amyloid structures is of particular interest, since the amyloidosis of the light chains of transthyretin and immunoglobulins contributes to amyloid deposition in soft tissues." (PMID 34641582, 2021). "For a few applications, including engineering T-cells for cancer therapy, inborn blood disorders, transthyretin (TTR) amyloidosis, and heritable blindness, CRISPR-therapies have become available to patients." (PMID 34539755, 2021). "Predicting the symptoms and rapidity of progression from the patient’s TTR genotype is difficult due to the variability of ATTRv amyloidosis." (PMID 34602081, 2021). "Recently, patisiran, a short interfering RNA, and inotersen, an antisense oligonucleotide, were shown to reduce the production of TTR and have become available for ATTRv amyloidosis patients." (PMID 34361762, 2021). "Amyloid transthyretin (ATTR) amyloidosis with polyneuropathy (PN) is a progressive, debilitating, systemic disease wherein transthyretin protein misfolds to form amyloid, which is deposited in the endoneurium." (PMID 31907599, 2021). "Transthyretin amyloid (ATTR) cardiomyopathy is a debilitating disease leading to heart failure and death." (PMID 34035264, 2021). "Transthyretin (ATTR) amyloidosis is categorized into hereditary and wild-type amyloidosis on the basis of sequencing of the TTR gene." (PMID 34957240, 2021). "As new disease-modifying therapies emerge, a complete understanding of the molecular mechanisms subserving the development of TTR amyloidosis will provide helpful insights into the heterogenic manifestations of this misfolding disease." (PMID 34884963, 2021). "Cardiac involvement varies among types of amyloidosis, most commonly found in immunoglobulin light chain (AL) and transthyretin (ATTR) amyloidosis." (PMID 32372287, 2021). "With an autosomal dominant mode of inheritance, hereditary TTR (ATTRv) amyloidosis typically becomes symptomatic with a progressive sensorimotor and autonomic neuropathy and cardiac dysfunction." (PMID 34719408, 2021). "The specific amyloidogenic protein determines the sub-classification of the amyloidosis with immunoglobulin light chain (AL), transthyretin (ATTR), and serum amyloid A (AA) as the most important and frequent ones." (PMID 35008745, 2021). "TTR amyloidosis has been reported in a group of 25 diseases, including AD, owing to TTR deposition in the brain." (PMID 33670947, 2021). "Nerve biopsy represents the gold standard to demonstrate amyloid deposits in patients with amyloid neuropathy, both in immunoglobulin light-chain (AL) amyloidosis and transthyretin (TTR)-related amyloid neuropathy." (PMID 33498362, 2021). "The first LNP-siRNA drug, Onpattro®, for the treatment of transthyretin-mediated amyloidosis, was approved in 2018." (PMID 34068715, 2021). "TTR amyloidosis is initiated by the dissociation of the tetramer into monomers, which is followed by deformation into misfolded monomers, non-native oligomers, and finally amyloid fibrils." (PMID 33922648, 2021). "It has been shown that doxycycline acts as L55P TTR amyloid fibril disruptor in vitro and disaggregates amyloid deposits in V30M TTR transgenic mice with a concomitant decrease of various amyloidosis tissue markers." (PMID 35008816, 2021).
amyloidosis (continued). "The three most common types of amyloidosis affecting the heart (“cardiac amyloidosis”) are AL, ATTRwt, and mutant transthyretin (ATTRm) amyloidosis." (PMID 34062949, 2021). "It becomes vital to differentiate AL amyloidosis from transthyretin (TTR) amyloidosis, another disease of increasing prevalence, due to the difference in management." (PMID 34006856, 2021). "Structural stabilizers such as tafamidis and diflunisal can block the dissociation of TTR tetramer and facilitate the treatment of patients with TTR amyloidosis." (PMID 33679409, 2021). "Among the more than 30 proteins that can make up amyloidosis, light chain monoclonal (AL) and transthyretin (ATTR) are the most common." (PMID 33494357, 2021). "We present a young patient of wild-type transthyretin amyloidosis, contradicting its only senile presence." (PMID 33907095, 2021). "Amyloids formed by the protein transthyretin (TTR) are at the origin of several amyloidoses (ATTR) that can be divided in two main types: sporadic, age-related amyloidosis, and hereditary or familial amyloidosis." (PMID 35008816, 2021). "Transthyretin (TTR) amyloidosis (ATTR) is the most common type of systemic amyloidosis and is classified into a hereditary type (ATTRv), and a wild type transthyretin (ATTRwt) amyloidosis." (PMID 34640569, 2021). "This different ligand recognition should be taken into consideration for future design of TTR amyloidosis inhibitors." (PMID 32419519, 2020). "Transthyretin (TTR) is a homotetrameric protein involved in human amyloidosis, including familial amyloid polyneuropathy (FAP)." (PMID 32998442, 2020). "MS analysis of proteins from amyloid deposits, moreover, allowed dissecting a heterogeneous series of C-terminal transthyretin fragments in ATTRwt amyloidosis." (PMID 32952127, 2020). "AL amyloidosis usually involves abnormal light chains as the amyloidogenic precursor whereas TTR amyloidosis involves an abnormal production of the amino acid transthyretin." (PMID 33195479, 2020). "Modern treatments that stop the synthesis of TTR through gene silencing, such as patisiran and inotersen, have shown positive results for patients with TTR amyloidosis." (PMID 32328845, 2020). "Patisiran (Onpattro®) is the first LNP–siRNA formulation to have been approved by the U.S. Food and Drug administration (FDA) for the treatment of hereditary transthyretin (hTTR) amyloidosis." (PMID 32580326, 2020). "Across the clinical development program, patisiran has demonstrated robust, rapid, and sustained reduction of TTR in patients with hATTR amyloidosis." (PMID 32641071, 2020). "Here, using photo-induced cross-linking of unmodified proteins (PICUP), we studied the early stages of oligomerization of human transthyretin (TTR), a plasma protein involved in amyloid diseases (ATTR amyloidosis) with multiple clinical manifestations." (PMID 33287192, 2020). "A prominent representative of RNAi-triggering therapeutics is the first FDA-approved siRNA drug Patisiran against hereditary transthyretin-mediated amyloidosis." (PMID 33339365, 2020). "In current practice, TTR amyloidosis has been divided into two amyloid diseases referred to as wild type and familial." (PMID 33203794, 2020). "The TTR-induced endothelial cell damage and direct compression of blood vessels by amyloid deposits likely contribute to microangiopathy in FAP." (PMID 32604774, 2020). "Two types of amyloid commonly infiltrate the myocardium—immunoglobulin light chain (AL or primary systemic) amyloid and transthyretin (TTR) amyloid." (PMID 32648130, 2020). "For example, onpattro (patisiran, Alnylam Pharmaceuticals) was the first siRNA drug, which was approved for clinical use to treat patients with hereditary transthyretin-mediated (hATTR) amyloidosis by the US Food and Drug Administration (FDA) in 2018." (PMID 33604354, 2020).
amyloidosis (continued). "Patisiran uses a specific siRNA against transthyretin mRNA, and has been shown to reduce transthyretin protein levels sufficiently enough for the successful treatment of transthyretin-mediated amyloidosis." (PMID 33113880, 2020). "Typing of the precursor protein (TTR) and the amyloid fibril type was available for 82 (89%) of the patients with ATTRv amyloidosis and proven amyloid deposits in their first fat pat biopsy." (PMID 33032630, 2020). "Separate clinical trials of effectiveness of treatments for wild type TTR and familial TTR amyloidosis are unnecessary and counterproductive." (PMID 33203794, 2020). "Presently, therapeutic strategies and clinically approved drugs against TTR amyloidosis aim to stabilize the TTR tetramer or suppress TTR production." (PMID 33287192, 2020). "Treatment with TTR tetramer stabilizers (tafamidis: approved in EU and select regions for treatment of the polyneuropathy of hATTR amyloidosis; and diflunisal: used off-label for hATTR amyloidosis) has been shown to slow progression of neurologic impairment." (PMID 32641071, 2020). "Subsequently, siRNA is then released in the cell cytoplasm where it interacts with TTR mRNA, reducing TTR protein translation, thereby inhibiting the formation and deposition of amyloid plaques." (PMID 32604776, 2020). "Nearly all of the 150+ known mutations increase dissociation of the homotetrameric protein structure and increase the probability of an individual developing a TTR amyloid disease late in life." (PMID 33203794, 2020). "Another treatment approach arises from the observation that the TTR plasma concentration in an individual is maintained at a near constant value both before and after an amyloidosis develops." (PMID 33203794, 2020). "Transthyretin (TTR) can cleave Aβ, resulting in the formation of short peptides with less activity of amyloid plaques formation, as well as being able to degrade Aβ peptides that have already been aggregated." (PMID 33256250, 2020). "Amyloidosis begins when the rate of TTR proteolysis decreases relative to the rate of amyloid formation and monomer concentration increases sufficiently to allow significant oligomerization into fibrils and amyloids." (PMID 33203794, 2020). "Transthyretin (ATTR) amyloidosis is one of the major systemic amyloidoses and is induced by the deposition of misfolded transthyretin (TTR)." (PMID 33032630, 2020). "Tolcapone was also shown to be effective in treating amyloid transthyretin (ATTR) amyloidosis in vivo." (PMID 32425892, 2020). "The drug discovery effort focused on TTR amyloid diseases continues, exemplified by the discovery of the small-molecule stabilizer AG10, now in a phase 3 trial (NCT03860935)." (PMID 32998442, 2020). "Relying on a liposomal siRNA formulation, Patisiran downregulates transthyretin in the liver for the treatment of hereditary transthyretin-mediated amyloidosis (hATTR)." (PMID 32927826, 2020). "The first LNP delivering an RNAi therapeutic molecule to reach the market was patisiran in 2018—this drug lowers the hepatic levels of transthyretin for the treatment of hereditary transthyretin-induced amyloidosis." (PMID 32778947, 2020). "The common denominator of these approaches is to reduce the supply or to stabilize transthyretin, again stressing the importance of rapidly and profoundly turning off the supply of the amyloid-forming protein to treat amyloid diseases." (PMID 32754033, 2020). "Patisiran is the first FDA (US Food and Drug Administration)-approved siRNA drug to treat hereditary transthyretin-mediated amyloidosis (hATTR) by silencing transthyretin." (PMID 33251041, 2020). "Collectively, these clinical and laboratory observations paved the way for a novel therapeutic approach against TTR-related amyloidosis, that is TTR tetramer stabilization." (PMID 32754033, 2020).
amyloidosis (continued). "Transthyretin (TTR)‐related amyloidosis (ATTR), a rare and underdiagnosed disease, mainly affects the cardiac and peripheral nerves and is fatal if not treated in time." (PMID 32725834, 2020). "IgM hydrolyzing transthyretin with aberrant conformation, dissolving toxic species of this protein and protecting against the development of amyloidosis, has been found in healthy donors." (PMID 32751323, 2020). "ONPATTROTM (Patisiran), the first RNA interference (RNAi) therapeutic drug has been approved by FDA for the treatment of the polyneuropathy of hereditary transthyretin-mediated (hATTR) amyloidosis in adults." (PMID 33361528, 2020). "Preclinical and clinical investigation has documented the successful delivery of therapeutic siRNA by nanoparticles to treat transthyretin (TTR) mediated amyloidosis (NCT01960348) and cancers." (PMID 32193458, 2020). "Current treatment strategies for hATTR amyloidosis directed at disease pathophysiology include prevention of TTR protein production or stabilization of the TTR protein complex." (PMID 32641071, 2020). "Four patients received a heart transplant, three in the AL and one in the ATTRwt group, and one patient with TTR amyloidosis a LV assist device over the course of the study period." (PMID 31134330, 2020). "The wild type TTR gene underwent Darwinian selection for transporting thyroxine and retinol when reproductive age and life expectancy were much shorter than today and amyloidosis had negligible effect." (PMID 33203794, 2020). "Here we develop a unifying biophysical model that quantifies the relationships among these variables in plasma and suggest the probability of an individual developing a TTR amyloid disease can be estimated." (PMID 33203794, 2020). "In the retrospective analysis one patient had lower Ki than the highest Ki in controls; this subject had TTR-type of amyloidosis and cardiac involvement was confirmed by endomyocardial biopsy." (PMID 30039218, 2020). "Our study confirms the previous assumption that severe clinical cardiac manifestations in AGel amyloidosis are rather rare, especially when compared with other systemic amyloidoses, such as AL and transthyretin (ATTR) amyloidosis." (PMID 31952544, 2020). "More recently, an alternative therapeutic approach against TTR-related amyloidosis has been explored, one which is based on gene silencing." (PMID 32754033, 2020). "Reduction of liver-derived circulating mutant and wild type amyloidgenic TTR protein using patisiran, which acts by a similar mechanism, has been shown to improve the polyneuropathy disease manifestations of hATTR amyloidosis." (PMID 31821125, 2020). "The second day of the conference was initiated by Dr. Juan Lopez-Mattei who discussed the diagnosis and management of amyloidosis, both transthyretin (TTR) and light chain (AL)." (PMID 32944289, 2020). "Investigational ASOs for Huntington’s disease (HD), amyotrophic lateral sclerosis (ALS) and transthyretin (TTR) amyloidosis, such as RG6042, tofersen and inotersen, respectively, are currently in phase III clinical trials." (PMID 32760425, 2020). "More than 40 severe degenerative disorders associated to at least 30 human proteins have been inserted in a group of pathologies called amyloidosis, and transthyretin (TTR) represents one of them." (PMID 32419519, 2020). "It has been reported that several natural compounds binding to transthyretin (TTR) can be useful in amyloidosis prevention." (PMID 32419519, 2020). "The beneficial effect and tolerability of patisiran treatment, reported here and in the APOLLO study, demonstrate the clinical impact of reducing TTR in patients with hATTR amyloidosis." (PMID 32641071, 2020). "The literature examination here reported gives a temporal view of the studies performed on natural compounds as inhibitors of TTR amyloidosis." (PMID 32419519, 2020).
amyloidosis (continued). "The Phase 3 ENDEAVOUR study evaluated revusiran, an investigational RNA interference therapeutic targeting hepatic transthyretin (TTR) production, for treating cardiomyopathy caused by hereditary transthyretin-mediated (hATTR) amyloidosis." (PMID 32062791, 2020). "Mass spectrometry analysis of the bladder biopsy specimen confirmed wild-type transthyretin (ATTRwt) amyloidosis consistent with senile systemic amyloidosis." (PMID 31983923, 2020). "Next, we assessed the presence of amyloid in calcified valves using Thioflavin S and congo red staining as well as by immunohistochemistry for TTR and Aβ—all used in clinical routine for detecting TTR-containing amyloid deposits and/or Aβ deposits." (PMID 32987857, 2020). "This therapeutic ON (Patisiran) represents the first FDA-approved siRNA with activity against hereditary transthyretin-mediated amyloidosis and was granted breakthrough status due to previous lack of an according drug." (PMID 33339365, 2020). "This is a quite relevant number (twice compared to Pompe disease) that is possibly related to the recent availability of personalised therapy (TTR gene silencing); for TTR-related amyloidosis together with the small size of the gene (4 exons)." (PMID 32946487, 2020). "These immunotherapies were successful to recognize circulating TTR and reduce TTR amyloidosis in vitro." (PMID 32566091, 2020). "One therapeutic strategy against TTR amyloidosis is the tetramer stabilization by small molecules such as bisaryl or monoaryl structure-based compounds or natural molecules." (PMID 32456156, 2020). "ONPATTRO® is a lipid-based siRNA nanoparticle designed to downregulate transthyretin in the liver for treatment of the polyneuropathy of hereditary transthyretin-mediated amyloidosis (hATTR)." (PMID 31726756, 2019). "Here the authors combine neutron crystallography, native mass spectrometry and modelling studies to characterize the T119M and S52P-TTR mutants, providing mechanistic insights into TTR amyloidosis." (PMID 30804345, 2019). "Amyloid fibrils formation of mutant and wild-type TTR are responsible for ATTRm and ATTRwt amyloidosis, respectively." (PMID 30704121, 2019). "Proteins, well known from other amyloidoses like amyloid A (AA), prealbumin/transthyretin (PA), apolipoprotein A-I (ApoAI), and amyloid P component (APC), and also keratin were found with variable intensities in the cases." (PMID 31531279, 2019). "We aimed to review the current knowledge on the epidemiology, diagnosis, and management of urinary and sexual dysfunction in patients with TTR amyloidosis (ATTR)." (PMID 31452024, 2019). "The homotetrameric plasma protein transthyretin (TTR), is responsible for a series of debilitating and often fatal disorders in humans known as transthyretin amyloidosis." (PMID 31835306, 2019). "With longer survival of myeloma and AL amyloidosis patients and increasing prevalence of patients with wild-type transthyretin amyloidosis due to an aging population, the phenomenon of two amyloid types in a single patient will be encountered more frequently." (PMID 30837451, 2019). "The amyloid fibril in hereditary transthyretin (TTR) Val30Met (pVal50Met) amyloid (ATTR Val30Met) amyloidosis is composed of either a mixture of full-length and TTR fragments (Type A) or of only full-length TTR (Type B)." (PMID 30811423, 2019). "LNPs are the most advanced delivery vehicle, and the Food and Drug Administration (FDA) approved LNPs for the treatment of the hereditary condition TTR-mediated amyloidosis in 2018." (PMID 31497026, 2019). "TTR amyloidosis is a rare life-threatening disease with complex phenotype–genotype correlations characterized by strong variability in penetrance, age of onset, and clinical symptoms." (PMID 30813263, 2019). "Another autopsy data study demonstrated that TTR amyloidosis occurs in the left ventricular myocardium in 32% of patients with HFpEF who are older than 75 years old." (PMID 31718691, 2019).